VIM (vimentin)
Diseases named in the same sentence as VIM in open-access papers (continued):
Sharing a sentence is not in itself a finding about the gene and the disease.
infection (continued). "Hence, these findings suggest that vimentin exerts a substantial effect on the replication of the velogenic variant NDV strain, whereas it does not affect the mesogenic strain during infection." (PMID 37848995, 2023). "Overexpression of VIM in HEK-293 cells only moderately enhanced SARS-CoV-2 infection, but either coexpression of VIM with ACE2 or treatment of HEK-293 cells expressing ACE2 with CM containing extracellular VIM significantly increased the level of infection of HEK-293 cells." (PMID 35078919, 2022). "Furthermore, the intracellular cholesterol levels in KO-vimentin cells infected with virus was higher than that of KO cells without infection." (PMID 36016436, 2022). "Collectively, this suggests that the BspC–K19 interaction may allow GBS to establish colonization of the FRT, but during EMT induction, interaction with vimentin may allow GBS adherence to exfoliating cells, resulting in the observed increase in ascending infection." (PMID 36069447, 2022). "However, infection as measured by luciferase activity 48h later was not affected, possibly due to dissociation of the vimentin-virus complexes." (PMID 33672181, 2021). "The anti-vimentin antibody alone was not sufficient to block EV-A71 infection completely." (PMID 31924205, 2020). "Having demonstrated that all three cell lines expressed vimentin at the cell surface which colocalized with the viral particles, we next set out to investigate whether it also affected HPV16-PsV internalization, leading to infection." (PMID 28566373, 2017). "However, the bacterial entry into brain, PMN transmigration across the BBB, and BBB permeability indicated by albumin concentration in CSF were all significantly reduced in vimentin knockout and with IbeA deletion (ZD1) as compared to wild-type mice with E44 infection." (PMID 27657497, 2016). "Infection with JEV did not enhance the vimentin expression in mature neurons." (PMID 25517725, 2014). "Finally, whether HCV manipulates vimentin secretion or membrane distribution dynamically during infection, as for SARS-CoV-2 and other viruses, has not been systematically examined." (PMID 41516263, 2025). "However, rsCDM could provide reliable results within 4 h for classification of carbapenemases (KPC, NDM, VIM, IMP, KPC, and NDM) and AmpC enzymes with abnormalities in blaOmpK35/blaOmpK36, which is more beneficial for therapeutic decision and infection control." (PMID 35572690, 2022). "However, the cells lacking O-GlcNAc on vimentin were resistant to infection by Chlamydia bacteria." (PMID 29513221, 2018). "Given that vimentin is SUMOylated during A. phagocytophilum infection and that both vimentin and SUMOylation are important for A. phagocytophilum growth, vimentin SUMOylation is likely not a host response induced by infection but rather is a pro-microbial, bacterial-driven process." (PMID 29056733, 2016). "However, we still observed a cage-like vimentin structure around the inclusion in our Chlamydia-infected cells, which suggests that this reorganization of the host cytoskeleton during an infection does not require vimentin cleavage." (PMID 22876181, 2012). "Genetic removal of vimentin markedly and specifically disrupts HCV cell–cell transmission without influencing cell‐free infection." (PMID 39611409, 2025). "Similar to the pro-viral role observed in EV71, vimentin forms cage-like structures with FMDV nonstructural proteins 2C and 3A during infection." (PMID 41516263, 2025). "Taken together, these results suggest that the different intracellular distribution of vimentin between DH82Ond pi and non‐infected controls might be correlated to the predominant cellular phenotype among each cell population, rather than to the infection status." (PMID 32627957, 2020).
infection (continued). "Infection with 5 MOI of EpCAM-WT lentiviral particles did not affect E-cadherin expression; however, dose dependent treatments of 2, 5, and 10 MOI of EpCAM-L240A lentiviral particles induced ZEB1 and vimentin expression and suppressed E-cadherin expression." (PMID 37192201, 2023). "Firstly, we found that, while Angiotensin-converting enzyme 2 (ACE2) is expressed in these cells, blocking ACE2 by antibody treatment did not prevent infection by SARS-CoV-2 spike pseudovirions, nor did antibody blockade of extracellular vimentin and other cholesterol-rich lipid raft proteins." (PMID 37511618, 2023). "Furthermore, stable infection with GATA1 wt, but not GATA1 S161A S187A mutant resulted in decreased E-cadherin expression and increased fibronectin, vimentin expression in MCF-7 cells or NMuMG cells." (PMID 25726523, 2015). "The mesenchymal marker vimentin/VIM was repressed by infection (FC, −2.22), whereas common markers of EMT (e.g., CDH1/2, SNAI1/2, and ZEB1/2) were not differentially expressed, suggesting that infection does not induce EMT in endocervical epithelial cells at 24 hpi." (PMID 37874141, 2023). "Together, these data suggest that the observed vimentin-mediated effect on HPV internalisation at early time points of infection is transient and only impacts the very early steps of viral/host cell engagement and internalisation but is not sustained at long-term infection time points." (PMID 34960740, 2021). "We propose that AnkF recruits vimentin to the CCV, as AnkF partially localizes to the CCV and the timing of recruitment of vimentin to the CCV correlates with effector protein translocation, which starts not earlier than 8 h and peaks around 24 h post-infection." (PMID 33282747, 2020). "Thus, the upregulation of vimentin, at day 1 pi, might be an indirect effect provoked by E75CV1 infection on surrounding non-infected cells." (PMID 30208957, 2018). "The results revealed that the miR-200c overexpression in the tumors led to a marked reduction of ZEB1 mRNA, Vimentin mRNA and the protein expressions compared with the CD44+CD117+CSCs with lentivirus mock and with the CD44+CD117+CSCs without lentivirus infection." (PMID 23842108, 2013).
adenocarcinoma (57 papers, 2006 to 2025). A common cancer characterized by the presence of malignant glandular cells. "Multifocal loss of CK14 and vimentin staining (myoepithelial cells) was observed in the adenocarcinomas despite all the apocrine gland and CGTs expressing CK7+/CK14+." (PMID 40281972, 2025). "The decreased levels of post-translationally modified glycosylated-vimentin intermediate filaments are associated with the progression of adenocarcinoma." (PMID 35573702, 2022). "CD26-expressing adenocarcinomas showed a higher expression of Vimentin and Elastin (p = 0.0027 and p < 0.0001, respectively), while E-cadherin expression was lower in this group of patients (p = 0.0021)." (PMID 41426321, 2025). "These long-lived (unubiquitinated) vimentin intermediate filaments activate AKT-driven metastasis of adenocarcinoma." (PMID 35573702, 2022). "The survivor showed an “epithelial-type adenocarcinoma with plasmacytoid dedifferentiation”, with membrane positivity for E-cadherin and β-catenin and vimentin negativity." (PMID 31205468, 2019). "Vimentin staining of lung sections of adenocarcinomas and bronchioles from control and Nanos3 NSCLC mice showed similar vimentin expression patterns for control and Nanos3 NSCLC mice." (PMID 31208373, 2019). "In primary adenocarcinoma of the colon, IL-6R expression has been positively correlated with EMT-associated mesenchymal markers SNAIL, SLUG, VIM, ZEB1, and ZEB2." (PMID 31741710, 2019). "Single cell gene analysis showed that some SCCs positive for KRT14 expressed the adenocarcinoma marker KRT8 as well as the EMT markers VIM, and ZEB2." (PMID 29079795, 2017). "In this case, pathologic examination revealed an adenocarcinoma-like mass exhibiting expression of Vimentin and CD99 as well as focal expression of CK." (PMID 23251173, 2012). "Loss of cytokeratins and increased expression of vimentin, smooth muscle actin, or fibronectin have been shown to occur concurrently with EMT in adenocarcinomas." (PMID 20609236, 2010). "Furthermore, CD26-expressing adenocarcinomas showed a higher expression of the EMT phase markers Vimentin and Elastin." (PMID 41426321, 2025). "Similar to the mRNA levels, E-cadherin protein was seen in lung epithelial cells (mainly bronchiole) and detected in adenocarcinomas, while vimentin (positive in myoepithelial cells of control lungs) and snail proteins (negative in lung) were detected in PSC tumors by Immunohistochemistry." (PMID 35954335, 2022). "Vimentin expression in adenocarcinomas and bronchioles of control and Nanos3 NSCLC mice." (PMID 31208373, 2019). "Particularly, in adenocarcinomas E2F2 expression correlated with EMT marker vimentin." (PMID 29072692, 2017). "Also we observed elevated expression level of mesenchymal markers including Snail, Zeb1 and Vimentin in matched lung tumors from adenocarcinoma patients compared to normal adjacent tissues." (PMID 25970786, 2015). "One hypothesis may be that since A549 cells are an adenocarcinoma cell line and likely exhibit increased mesenchymal characteristics than normal epithelial cells, such as greater production of vimentin and actin." (PMID 24040294, 2013). "Pulmonary tissue and corresponding cell blocks of MPE samples from 20 patients with primary adenocarcinoma were analyzed by immunohistochemical staining with CSC-representative markers (CD133, Nanog, and OCT-4) and EMT-associated markers (E-cadherin and vimentin)." (PMID 23658677, 2013). "The levels of Vimentin and Elastin were significantly higher in CD26-positive tumors compared to CD26-negative adenocarcinoma tissues (p = 0.0027 and p < 0.0001, respectively)." (PMID 41426321, 2025). "Heatmap analysis revealed upregulated VIM and PLK1 mRNA expression in TGF-β-treated adenocarcinoma when the mesenchymal markers CDH2, SNAI1, and SNAI2 were high and either CDH1 or OCLN (epithelial markers) was low in majority of LUAD cells analysed." (PMID 33963314, 2021).
adenocarcinoma (continued). "In adenocarcinoma patients, EDIL3 expression was significantly correlated with low e-cadherin expression (P < 0.001), high vimentin expression (P = 0.001), and increased microvessel density (P = 0.023)." (PMID 28819306, 2017). "A combination of “generic” adenocarcinoma markers (CK7, CK19, BerEP4, and polyclonal CEA) together with vimentin and a limited number of “pancreatobiliary” markers (MUC1 and CA19-9) defines its characteristic immunohistochemical profile." (PMID 27829047, 2016). "The proportion of the MPP component in the five adenocarcinomas with lymphatic invasion was <25 and these MPP components exhibited vimentin expression at grade 3+." (PMID 25120667, 2014). "When mutant GFAP was transfected into non-astrocyte SW13vim- cells, an adenocarcinoma cell line lacking vimentin, GFAP aggregates were formed." (PMID 39596168, 2024). "In veterinary field, vimentin, E-cadherin, pancytokeratin, Wilms tumor 1 (WT1), MUC-1, and calretinin were used to differentiate between reactive mesothelial cells, malignant mesotheliomas, and adenocarcinomas in large felids only through post-mortem." (PMID 37480011, 2023). "We further performed IHC analysis in two Skip N2—Adenocarcinoma and two Non-Skip N2-Adenocarcinoma samples using E-cadherin and Vimentin antibodies in order to confirm our PCR results." (PMID 35201505, 2022). "A subcutaneous deposit was biopsied, disclosing an adenocarcinoma positive for cytokeratins and negative for vimentin." (PMID 23758919, 2013). "Cases of adenocarcinoma lacking expression of either myosin IIA or vimentin show a good outcome without PAC, and therefore do not require such treatment." (PMID 18212748, 2008). "Expression of vimentin was absent in normal and adenocarcinoma tissues, but present in over a third (36%) of PMP tissues (P=0.004)." (PMID 17031402, 2006). "Therefore, the negative expression of Vimentin and ER further supports adenocarcinoma of cervical origin." (PMID 40823095, 2025). "The expression of the pluripotency genes OSKM, the adenocarcinoma marker NKX2-1, the lung surfactant proteins SFTP, the myofibroblast marker MYH and DNMT3A/3B was analyzed with qRT-PCR and the presence of the myofibroblast markers vimentin and α-SMA with immunofluorescence." (PMID 35081981, 2022). "There may also be additional signals required for the cell to translate the VIM transcript once it has accumulated, as suggested by a report of a MAP kinase-interacting kinase inhibitor which abolished increase in VIM protein, but not in VIM mRNA during EMT in MDA-MB-231 adenocarcinoma cells." (PMID 27876705, 2016). "Our results showed that more than 90% of cases diagnosed as primary adenocarcinoma of the gallbladder were positive for CK7 (97.6%), CK19 (98.2%), CKLMW (100%), CKHMW (91.6%), or MUC1 (97.1%) expression, or were negative for vimentin (96.1%) or MUC2 (96.9%)." (PMID 33494186, 2021). "In three of the adenocarcinomas with no MPP components, vimentin expression was found to be negative, and in two others, vimentin expression was observed to be grade 2+ and 1+." (PMID 25120667, 2014). "Ovaries were normal, but the adnexal biopsy disclosed an adenocarcinoma positive for CK7, CK8, CK19, CA125, and PR and negative for CK20, CEA, TTF1, CA19-9 and vimentin." (PMID 23758919, 2013). "However, adenocarcinoma is generally positive for CEA, TTF-1, and napsin A and negative for calretinin and vimentin, whereas in MM, the scenario is reversed." (PMID 38938650, 2024).
bacterial infections (18 papers, 2015 to 2025). "Thus, the upregulation of vimentin may be associated with changes in intestinal integrity as vimentin gene expression has been shown to increase during bacterial infection." (PMID 26575181, 2015). "The roles of vimentin on SCVs uncovered in this study improve our understanding of the dynamic cytoskeletal forces involved in bacterial infection and how the bacteria control these forces to their benefit." (PMID 36717589, 2023). "Vimentin has been shown to have different roles during bacterial infections, one of which is in transcellular migration and adhesion of lymphocytes." (PMID 35336202, 2022). "Here, we highlight the main findings from investigations of the significance of vimentin in bacterial infections." (PMID 27096872, 2016). "Mechanistic insight is presented involving distinct bacterial virulence factors that target vimentin to subvert its function in order to change the host cell fate in the course of a bacterial infection." (PMID 27096872, 2016). "Additionally, vimentin is secreted and found extracellularly, where it primarily regulates inflammation induced by bacterial infections." (PMID 40061451, 2025). "Hence, given the multiple localizations of vimentin, several therapeutic strategies have been developed to target vimentin in light of tumorigenesis and viral and bacterial infections." (PMID 37475865, 2023). "Besides, SPI-1 effector SipB and SPI-2 effectors are inessential in regulating vimentin rearrangement, which were evidenced by ΔsipB and ΔphoP bacterial infection." (PMID 36717589, 2023). "To examine whether Cdc42 is involved in SCV maintenance regulated by SopB and vimentin, we examined the subcellular localization and the active level of Cdc42 upon bacterial infection." (PMID 36717589, 2023). "Accumulating evidence supports the idea that vimentin plays diverse role in bacterial infections." (PMID 35921364, 2022). "Interestingly, vimentin also involves in many cellular processes such as cell adhesion, cellular signalling, autophagy, and bacterial infections." (PMID 35853077, 2022). "Extracellular vimentin has a vital role in various viral and bacterial infections." (PMID 34299089, 2021). "Indeed, an increasing number of reports have demonstrated a diverse role for vimentin in bacterial infections, primarily in innate host cell defense mechanisms and pathogen adhesion and invasion." (PMID 29487235, 2018). "Given that vimentin and its assembly at the ApV are pro-microbial in A. phagocytophilum infection and in other bacterial infections, this study highlights a potentially conserved mechanism by which intracellular pathogens exploit intermediate filaments for survival." (PMID 29056733, 2016). "In addition, we found the SGC3 group expressed a cohort of immune-related genes, such as vimentin (Vim) and interferon regulatory factor 1 (Irf1), indicating these cells might participate in defending DRGs against viral or bacterial infections." (PMID 39083491, 2024). "Here, we summarize the knowledge about the role of IFs in bacterial infections, focusing on the type III IF protein vimentin." (PMID 27096872, 2016). "During the bacterial infection, SRR protein SssP1 is exported to assemble a fimbria-like component, which drives a strong binding effect with the BBB depending on the sialylation of vimentin." (PMID 35853077, 2022). "However, vimentin failed to aggregate post ΔsopB bacterial infection in several cell lines, including U2OS, MEFs and RAW 264.7." (PMID 36717589, 2023).
neurodegenerative disease (11 papers, 2011 to 2024). A disorder of the central nervous system characterized by gradual and progressive loss of neural tissue and neurologic function. "Lastly, Vim encodes for vimentin, which is a marker of reactive astrocytes in reactive gliosis, and its expression is increased in neurodegenerative diseases." (PMID 38248237, 2023). "VIM is an intermediate filament that maintains astrocyte integrity and is over-expressed after CNS injury or neurodegenerative diseases." (PMID 35145378, 2021). "Vimentin is overexpressed by astrocytes after a nervous system injury or in neurodegenerative diseases and is a reliable indicator of reactive astrocytes in various experimental models." (PMID 33050187, 2020). "This aspect merits further studies of the function of vimentin in neurodegenerative diseases, to elucidate the contribution of IFs to the progression or attenuation of disease emergence." (PMID 28841900, 2017). "These consisted of markers of astrocytic and microglial activation (GFAP, vimentin, galectin-1, and clusterin) and indicators of neurodegenerative disease (ApoE and serpinA3N) that each demonstrated significant prion effects and PAM effects from the MS proteomic analysis." (PMID 36378750, 2022). "Since the cytoskeleton plays an important role in the pathogenesis of neurodegenerative diseases including AD, particular attention was focused on the effect of indicaxanthin on some cytoskeletal proteins such as Vimentin and GFAP, which have an important role in astrogliosis, a typical sign of AD." (PMID 33806203, 2021). "Some authors report that cytoskeleton proteins, such as vimentin and GFAP, are involved in several cellular functions and in stress conditions, so their expression is considered a biomarker of astrocyte activation and astrogliosis caused by lesions or neurodegenerative diseases." (PMID 39459191, 2024).
colorectal (9 papers, 2011 to 2025). "Our current findings may provide further evidence to support the notion that the activation of vimentin positive fibroblasts in the adenomatous/cancerous stroma might be one of the hallmarks of EMT and are involved in the process of colorectal tumorigenesis." (PMID 28484082, 2017). "Finally, 60 human lung ADC samples and 21 sets of matched specimens (primary and metastatic foci in lymph nodes from one patient) were used to confirm the clinicopathologic significance of FGF4 and its correlation with E-cadherin, Vimentin and Orai1 expression." (PMID 27677589, 2016).